NEU3 (neuraminidase 3)
Diseases named in the same sentence as NEU3 in open-access papers (continued):
Sharing a sentence is not in itself a finding about the gene and the disease.
heart failure (1 paper, 2020). Inability of the heart to pump blood at an adequate rate to meet tissue metabolic requirements. "Therefore, we investigated the roles of NEU1 and NEU3 in the heart exposed to I/R and observed that increased NEU1 expression and activation is associated with high inflammation and an increased risk of heart failure, while NEU3 had no such effects." (PMID 32975669, 2020). "Of note, in contrast to the C57BL/6 genetic background of hNEU1 mice, I/R did not lead to heart failure in WT mice of the FVB/N genetic background in which NEU1 and NEU3 transgenes were generated and therefore a potential benefit of NEU3 overexpression could not be assessed." (PMID 32975669, 2020).
liver disease (1 paper, 2024). "We observed that patients with liver disease also have increased desialylation of some serum proteins and elevated serum levels of NEU3 protein." (PMID 39570922, 2024).
liver fibrosis (1 paper, 2024). "In male mice, injections of DANA or the lack of NEU3 also attenuate high fat diet (HFD)-induced liver inflammation, and DANA inhibits methionine and choline-deficient (MCD) diet-induced liver fibrosis, indicating that NEU3 regulates liver inflammation in male mice." (PMID 39570922, 2024). "To determine if inhibiting NEU3 can inhibit liver fibrosis in the commonly-used CCl4 model, in this report, we examined the effects of injections of the NEU3 inhibitor 2-acetyl pyridine (2AP)." (PMID 39570922, 2024). "To further determine if NEU3 is part of an additional mechanism that drives liver fibrosis, in this report, we examined if inhibiting NEU3 can inhibit fibrosis in the CCl4 model in male and female mice." (PMID 39570922, 2024).
liver inflammation (1 paper, 2024). "We have demonstrated that the NEU3 inhibitor 2AP attenuates CCl4-induced liver inflammation, fibrosis, desialylation of proteins, and increased expression of NEU3 in both male and female mice." (PMID 39570922, 2024). "We have previously shown that DANA, or the lack of NEU3, both attenuate diet-induced liver inflammation and fibrosis in mice." (PMID 39570922, 2024).
lysosomal storage disease (1 paper, 2018). A metabolic disorder caused by mutations in proteins critical for lysosomal function, including lysosomal enzymes, lysosomal integral membrane proteins, and proteins involved in the post-translational modification and trafficking of lysosomal proteins. "Hence these cells follow the conventional theme of a lysosomal storage disease for the neu3-/-neu4-/- mouse model." (PMID 30359429, 2018).
malnutrition (1 paper, 2025). Inadequate nutrition resulting from poor diet, malabsorption, or abnormal nutrient distribution. "All these point to the direction of Neu3, indicating this enzyme is one of the key factors mechanistically involved in malnutrition." (PMID 40707594, 2025).
mastitis (1 paper, 2022). Inflammation of breast tissue during lactation or postpartum due to an obstructed duct or infection. "We therefore investigated the role of Neu3 in the development of mastitis by administering zanamivir, a specific Neu inhibitor, to mice." (PMID 36451232, 2022).
mucolipidosis type IV (1 paper, 2025). A lysosomal disease characterized by psychomotor delay, progressive visual impairment, and achlorhydria. "Furthermore, the expression level of Ccl5 (RANTES) was increased in Hexa-/-Neu3-/- mice, similar to mouse models of the Niemann Pick type C (Npc1-/-), Gaucher (Gba-/-) and mucolipidosis type IV (Mcoln1-/-), and this increase was reduced after KD and PG treatments." (PMID 40019557, 2025).
myocardial infarction (1 paper, 2022). Gross necrosis of the myocardium, as a result of interruption of the blood supply to the area, as in coronary thrombosis. "The current study reports that Neu3 levels are significantly reduced during the reperfusion phase after myocardial infarction in a mouse model of IRI after LAD ligation." (PMID 35682772, 2022).
progressive multifocal leukoencephalopathy (1 paper, 2013). Progressive multifocal leukoencephalopathy (PML) is a neurological disorder that damages the myelin that covers and protects nerves in the white matter of the brain. "The progressive multifocal leukoencephalopathy (Pml) is related to retinoic acid receptor (RAR) activation and PPAR signaling, and the neuraminidase 3 (Neu3) to ceramide pathway and to p38MAPK." (PMID 23637839, 2013).
prostate neoplasm (1 paper, 2021). A neoplasm (disease) that involves the prostate gland. "The plasma membrane-associated sialidase NEU3 is upregulated in various types of cancer including renal, colon and prostate neoplasms." (PMID 34683168, 2021).
steatosis (1 paper, 2024). Increased lipid within the cytoplasm of cells. "In this report, we show that 2AP, a potentially specific NEU3 inhibitor, did not modulate steatosis, and had only a modest effect on weight change in female mice." (PMID 39570922, 2024). "However, DANA also inhibited diet-induced weight gain and reduced liver steatosis, whereas NEU3-/- knock out mice were not resistant to diet-induced weight gain and steatosis." (PMID 39570922, 2024). "Injections of DANA also inhibited HFD induced weight gain and steatosis, whereas NEU3-/- knock out mice were not resistant to HFD-induced weight gain and steatosis, suggesting that NEU3 does not regulate HFD-induced weight gain and steatosis." (PMID 39570922, 2024).
cancer (31 papers, 2009 to 2024). A tumor composed of atypical neoplastic, often pleomorphic cells that invade other tissues. "In cancer, the expression levels of these gangliosides are mainly regulated by the availability of glycosyltransferases and NEU3, a plasma membrane-associated sialidase specific for gangliosides." (PMID 34064863, 2021). "This area contains several candidate genes including the Neu3 gene (Human plasma membrane-associated sialidase) which is upregulated in several human cancers and is known to interact with EGFR." (PMID 19594952, 2009). "In response to the increase, cell surface associated sialidase (NEU3) may be secreted from the cell surface as hypothesized in cancer, which could account for the elevated serum sialidase activity in our study." (PMID 38978616, 2024). "In addition, a sialidase NEU3 associated with plasma membrane is often upregulated in carcinogenesis, metastasis, and invasiveness, while it suppressed the apoptosis of cancer cell." (PMID 31717732, 2019). "NEU3 is upregulated in various cancer types and is predicted to be involved in cell invasion and motility." (PMID 38255300, 2024). "In contrast to various carcinomas, we also reported a case in which NEU3 expression was reduced in cancer cells." (PMID 38255300, 2024). "In this study, all the selected cancer cell lines showed higher expression or activity of NEU3 than that in normal tissue-derived cell lines, although there were differences depending on the cell line." (PMID 38255300, 2024). "Sialidase NEU3, a key glycosidase for ganglioside degradation, is upregulated in various human cancers, increasing cell invasion, motility, and survival of cancer cells, possibly through activating epidermal growth factor (EGF) signaling." (PMID 38203236, 2023). "Lee and colleagues propose that NEU2 and NEU3, expressed in cancer cells, play a role the impaired function of natural killer cells, thus helping cancer cells in terms of immune escape." (PMID 36009856, 2022). "Collectively, the development of glycosyltransferase inhibitors or inducers, NEU3 inhibitors, and nucleic acid drugs, including siRNA targeting glycosyltransferase or NEU3, can be expected as future cancer therapy." (PMID 34064863, 2021). "High expression of neuraminidase NEU3 in cancer cells leads to protection against programmed cell death, while in contrast, decreased NEU3 induces apoptosis, implying a critical role of NEU3 in the survival of cancer cells." (PMID 31897224, 2020). "Human NEU3 is markedly up–regulated in various cancers and it has been shown to suppress apoptosis in cancer cells." (PMID 31801289, 2019). "Initially, we compared the status of Neu1/Neu2/Neu3/Neu4 in cancer and normal tissue specimens by immunohistochemistry." (PMID 29434218, 2018). "NEU3 enhances cancer cell survival, cell migration and attachment, whereby it stimulates Ras activation with a consequent influence on ERK1/2 and Akt and actually enhances the EGF-stimulated tyrosine-phosphorylation of EGFR." (PMID 25803810, 2015). "Because these data show a significant connection between NEU3 and apoptosis resistance in cancer, the sialidase NEU3 has been defined as a novel oncogene." (PMID 24625663, 2014). "NEU3 is often markedly up-regulated in human cancers and leads to apoptosis resistance, deregulation of the activation of EGFR, AKT, and Ras, and the expression of BCL-XL and BCL-2." (PMID 24625663, 2014). "The plasma membrane sialidase NEU3, which is deeply involved in ganglioside catabolism, has been demonstrated to play a key role in determining the survival of cancer cells." (PMID 24625663, 2014). "In contrast, NEU3 activity was confirmed in all of the four cancer cell lines." (PMID 38255300, 2024). "In malignant tumors, NEU3 promotes cell survival, migration, and adhesion." (PMID 34683168, 2021). "In conclusion, the serum ST6GalI/NEU3 level may represent a potential molecular factor to distinguish cSCC patients from non-cancer patients, pending further validation." (PMID 34683168, 2021).
cancer (continued). "As described in Section 2, increased NEU3 expression in cancer can be correlated with malignancy." (PMID 34064863, 2021). "Here, we found that NEU3 potentiates EGFR-mediated tumorigenesis through the stimulation of EGFR phosphorylation and Src activity, and these findings should provide a new tool for the development of cancer therapy by the suppression of NEU3 that activates EGFR-signaling." (PMID 25803810, 2015). "We previously demonstrated that sialidase NEU3, a key glycosidase for ganglioside degradation, is up-regulated in various human cancers, leading to increased cell invasion, motility and survival of cancer cells possibly through activation of EGF signaling." (PMID 25803810, 2015). "In addition, we demonstrated that human NEU3 is upregulated in terms of both enzymatic activity and mRNA level in many human cancers, including colon, renal, prostate, and ovarian cancers." (PMID 22815940, 2012). "Mice might be too prone to tumorigenesis to reproduce the protective effect of NEU3 seen in human cancer cells." (PMID 22815940, 2012). "Thus, NEU3 may be a potential target for cancer therapy as a molecule upstream of the EGFR/Src pathway, since the therapeutic efficacies of inhibitors for EGFR and Src have not been so encouraging despite many clinical trials for current anticancer therapies." (PMID 25803810, 2015). "In conclusion, the overexpression of NEU3 could cause the constitutive activation of EGFR together with Src activation in the presence of EGF, and subsequently potentiation of the tumorigenicity of cancer cells." (PMID 25803810, 2015). "Four mammalian NEU homologues are known so far—NEU1, NEU2, NEU3 and NEU4—of which NEU 1, 2 and 4 are downregulated in various cancers, resulting in sialoglycan accumulation in cancer cells." (PMID 30478534, 2019). "Mammalian sialidase is known to have 4 isoforms (NEU1, NEU2, NEU3 and NEU4) and plays many roles in cell functions including differentiation, growth, apoptosis and migration and in survival and proliferation of cancer cells." (PMID 24427265, 2014). "In detail, overexpression of NEU3 gives rise to activation of EGFR-downstream signaling, which in turn brings to survival of different human cancer cells." (PMID 24925219, 2014). "Taken together our data demonstrate that NEU3 regulates the DRM ganglioside content and it can be considered as a modulator of Akt phosphorylation, further supporting the role of this enzyme in cancer and tumorigenesis." (PMID 24925219, 2014). "The study by Cristina Tringali showed that the mRNA expression level of plasma membrane sialidase NEU3 in RCC is significantly higher than that of non-tumor tissues adjacent to cancer." (PMID 36010674, 2022). "In this context, it is assumed that co-overexpression of EGFR, c-Src and NEU3 in cancers is not just coincident but probably an essential event in tumorigenesis." (PMID 25803810, 2015). "The small interfering RNA-mediated knock-down of NEU3 in cancer cell lines, but not in normal cell-derived primary cultures, downregulates EGFR signaling and induces apoptosis." (PMID 22815940, 2012). "Taken together our data indicate that sialidase NEU3 is the enzyme responsible for the modifications of the ganglioside composition both in DRM and in non-DRM and can be considered as a modulator of Akt phosphorylation, further supporting its role in cancer and tumorigenesis." (PMID 24925219, 2014). "We therefore suggest that if EGFR is overexpressed, its activation can be increased by NEU3, but if EGFR is in a normal status, as in the normal intestinal mucosa, NEU3 activity is not able to transform EGFR into a cancer driver." (PMID 33233823, 2020).
tumor (16 papers, 2012 to 2025). "One possibility is that the tumor microenvironment attenuates the apoptosis induced by Neu3-deficiency in vivo." (PMID 22815940, 2012). "A second possibility is that mechanisms controlling cell growth and survival might have adapted to the Neu3-deficient conditions to allow tumor formation." (PMID 22815940, 2012). "In contrast, the expression level of NEU3 was significantly higher in tumor tissues than in normal tissues." (PMID 38255300, 2024). "We therefore took an experimental approach to test this idea using the Neu tumor due to its best-defined hierarchical structure from LPs (Neu-1) to AvPs (Neu-2) to AvDs (Neu-3)." (PMID 32840210, 2020). "In contrast, Neu1 and Neu3 were weakly expressed and lacked consistent tumor association, underscoring Neu2 as the dominant infiltrating subset." (PMID 40959269, 2025). "NEU3 plays an important role in tumor invasion and metastasis, but metastasis in cSCC is very rare." (PMID 34683168, 2021). "Their results indicated that NEU3 functioned in tumorigenesis via the EGFR/Src signaling pathway and led them to posit that inhibiting NEU3 might be a treatment option for delaying tumor growth by cells expressing GM3 as their major ganglioside." (PMID 32726962, 2020). "Optical density score conferred higher Neu1, Neu3, and Neu4 positivity in the tumor tissues." (PMID 29434218, 2018). "We previously demonstrated that NEU3 is up-regulated in tumor compared with that in adjacent non-tumor tissues in colon, renal, prostate and ovarian cancers, which may be regulated by Sp1/Sp3 transcriptional factors." (PMID 25803810, 2015). "Mechanistic studies using siRNA-mediated NEU3 knockdown revealed that reducing NEU3 expression suppressed extracellular signal-regulated kinase (ERK) and PI3K signaling, disrupting key pathways involved in tumor progression." (PMID 40252176, 2025). "In particular, NEU3 is up-regulated in most tumours, including NSCLC, where about one third of cases displays NEU3 overexpression at various levels (at either RNA or protein status)." (PMID 29088281, 2017). "However, Neu3 also has an MHCII antigen presentation gene (H2-Eb1), suggesting it may be a “hybrid” tumor promoting and tumor eliminating phenotype." (PMID 38265267, 2024). "Moreover, there is a lack of information about NEU3 expression and tumor sidedness in colorectal carcinogenesis." (PMID 33233823, 2020). "In addition, the mRNA levels of neuraminidase 3, an enzyme that hydrolyzes gangliosides, were higher in RCC tumor tissues than in non-tumor tissues, and overexpression of the gene resulted in decreased GM3 expression and increased lactosylceramide expression." (PMID 38612906, 2024).
infection (4 papers, 2016 to 2025). The state of being infected such as from the introduction of a foreign agent such as serum, vaccine, antigenic substance or organism. "Our qRT-PCR data revealed that sphingolipid metabolic key genes encoding enzymes: Cers2, Gba2, Gla, Asah1, Asah2, Acer2, Acer3, Neu3, Sgpp1, and Sphk1 were robustly upregulated in mRNA levels by the infection of C. sinensis." (PMID 36339341, 2022). "NEU1, which is commonly located at the lysosome and NEU3, found on cell surfaces, were induced during infection." (PMID 27389966, 2016). "Thus, a higher level of Neu3 in children suggests possible subclinical infection with such pathogens." (PMID 40707594, 2025).
liver (4 papers, 2020 to 2024). "For instance, in mice, injections of the sialidase inhibitor DANA, or the lack of NEU3 (Neu3−/− mice) attenuate diet-induced adipose tissue and liver inflammation, and DANA reduces liver steatosis." (PMID 36613682, 2022).
inflammation (3 papers, 2022 to 2024). Aberrant reaction of the microcirculation characterized by movement of fluid and leukocytes from the blood into extravascular tissues. "Our findings suggest that elevated levels of NEU3 in the lung are sufficient to induce lung inflammation and fibrosis." (PMID 35999554, 2022).
bacterial infection (1 paper, 2025). "Intestinal alkaline phosphatase prevents gut inflammation from subclinical bacterial infection that becomes impaired in the presence of neuraminidase-3 (Neu3) activity." (PMID 40707594, 2025).
neurological disorders (1 paper, 2018). "Disruption of Neu3 and Neu4 genes has led to the generation of a mouse model revealing severe neurological disorders." (PMID 30359429, 2018).
NEU3 also shares sentences with these, for which no sentence is quoted: cardiovascular disease (3 papers); adenocarcinoma (2); intestinal inflammation (2); Alzheimer disease (1); breast carcinoma (1); colon (1); colon adenocarcinoma (1); COVID-19 (1); galactosialidosis (1); GI inflammation (1); Glucose intolerance (1); heart disease (1); idiopathic pulmonary fibrosis (1); inflammatory bowel disease (1); influenza (1); ischemia (1); ischemic stroke (1); lymph node metastasis (1); metabolic disease (1); nephritis (1); neuroblastoma (1); pulmonary disorders (1); renal fibrosis (1); rheumatoid arthritis (1).